TOP1 (DNA topoisomerase I)
Diseases named in the same sentence as TOP1 in open-access papers (continued):
Sharing a sentence is not in itself a finding about the gene and the disease.
breast carcinoma (continued). "Of note, the rates of TOP1 and CDH3 positivity were the highest in BRCA1-related breast carcinomas (48%) followed by BRCA2-related (24%) and sporadic breast carcinomas (7%)." (PMID 27566577, 2016). "Based on the status of TOP1 CN, HER2 and estrogen receptors (ER), we then selected 9 breast cancer cell lines from the panel of the 52 characterized cell lines." (PMID 26801902, 2016). "TOP1 was reported to be highly expressed in liver cancer and breast cancer; however, its detailed mechanism has not been fully characterized." (PMID 37088855, 2023). "Thus, many studies have shown that the expression and/or co-expression of several genes, such as ERCC1, RRM1, TOP1, TOP2α, TUBB3, TYMS, and GSTP1, in tumor tissues is closely related to chemoresistance and prognosis in breast cancer patients (BC)." (PMID 35204496, 2022). "Moreover, camptothecin targets the nuclear enzyme topoisomerase I (TOP1) to treat endocrine-resistant breast cancer, and embelin is capable of inducing apoptosis in MCF-7 breast cancer cells." (PMID 36936274, 2022). "There was sparse evidence from level III retrospective studies and level IV pre-clinical studies supporting the chemosensitizing effect of TOP1 and TOP2A overexpression in response to camptothecin-based therapies and anthracyclines in gastrointestinal and breast cancers respectively." (PMID 27888622, 2017). "As a first step to evaluate clinical relevance, we analyzed protein expression of topoisomerase I (TOP1) and P-cadherin (CDH3) in a large panel of breast cancer tissues from BRCA1/2 mutation carriers and women without a hereditary predisposition." (PMID 27566577, 2016). "Breast cancer patients with ER-positive tumors expressing high WRN and Top1 had poor survival." (PMID 26959889, 2016). "Topoisomerase I (TOP1) and P-cadherin (CDH3) expression was investigated by immunohistochemistry on tissue microarrays of a large panel of 253 human breast carcinomas with and without BRCA1/2 mutations." (PMID 27566577, 2016). "We describe here potential molecular mechanisms of SN-38 resistance in breast cancer cells and sensitivity to other commonly used chemotherapeutic agents, as well as novel non-camptothecin Top1 targeting drugs." (PMID 26801902, 2016). "Similar to TOP1, increased CHD3 expression was associated with BRCA1/2-related breast carcinoma, independent of TNBC and age." (PMID 27566577, 2016). "Additionally, mining of breast cancer specific RNAseq data from TCGA, indicated a strong correlation between Top1 and WRN expression (r = 0.325, p = 5.83e-26) suggesting the importance of these two genes in breast cancer." (PMID 26959889, 2016). "TOP1 activity is not a marker for CPT sensitivity in breast cancer." (PMID 31783818, 2019). "To further explore this in breast cancer cells, we initially applied a FISH TOP1/CEN-20 probe mixture to a repository consisting of 52 human breast cancer cell lines to analyze the distribution of TOP1 and CEN-20 CN and the TOP1/CEN-20 ratios in these cell lines." (PMID 26801902, 2016). "Of 195 breast cancer samples with TOP1 and CDH3 available, 57 samples were positive for TOP1 and CDH3 and 138 samples were TOP1 and/or CDH3 negative (79 positive for either of the two markers and 59 samples negative for both markers)." (PMID 27566577, 2016).
colorectal cancer (35 papers, 2000 to 2025). A primary or metastatic malignant neoplasm that affects the colon or rectum. "Our investigation, which demonstrates the association between impaired removal of TOP1cc and defective NF‐κB activation and WRN deficiency, explains enhanced survival of colorectal cancer patients with WRN deficiency in response TOP1 inhibitor treatment." (PMID 35582959, 2022). "To rule out the tumor types as a variable, we narrowed the analysis to five types of tumor with the greatest number of TOP1 mutations – large intestine carcinoma, skin malignant melanoma, lung carcinoma, and stomach carcinoma." (PMID 35291312, 2022). "Hence, for prediction of the cellular CPT response, it may be informative to measure expression level, activity and CPT susceptibility of the TOP1 enzyme as previously demonstrated in experiments with colorectal cancer cell lines." (PMID 31783818, 2019). "Finally we investigated whether these three new TOP1 mutations were present also in biopsies from patients with colorectal cancer and whether they could be associated with their response to CPT-11." (PMID 21619602, 2011). "The Top1 poison camptothecin derivatives, topotecan and irinotecan, are used to treat solid tumors including ovary, cervix, pancreatic, lung, and colorectal cancers." (PMID 35280788, 2022). "Top1 and Top2 are mainly targeted due to their overexpression in many cancers including breast, cervix, and colorectal cancers." (PMID 35280788, 2022). "Survival of colorectal cancer patients with low expression of WRN was significantly increased after TOP1 inhibitor treatment." (PMID 35582959, 2022). "Hexadecanoic acid isolated from leaves of Kigelia pinnata showed the cytotoxic effect on HCT-116 (human colorectal cancer) by DNA topoisomerase I interaction." (PMID 33981211, 2021). "This study indicates that PTE and RE are inhibitors of Top1, which can effectively inhibit the DNA damage repair pathway mediated by Top1 and Tdp1, and induce apoptosis and death of a variety of colorectal cancer cells." (PMID 34439157, 2021). "In 1996, topotecan and irinotecan, drugs that are DNA topoisomerase I inhibitors, were approved for therapies of metastatic ovarian and colorectal cancers, respectively." (PMID 33297561, 2020). "Both gene copy number (CN), TOP1/centromere 20 (CEN-20) ratio, protein expression and mRNA expression have been used to identify expression levels of TOP1 in colorectal cancer but with conflicting outcome." (PMID 31196001, 2019). "Decreased levels of TOP1 protein in BC cells have been associated with decreased sensitivity to CPT; this finding is in line with data reported for colorectal cancer." (PMID 31783818, 2019). "Irinotecan (CPT-11), a water-soluble derivative of camptothecin, belongs to the class of DNA topoisomerase I inhibitors and has been approved worldwide for the treatment of advanced colorectal cancer, lung cancer, and malignant lymphoma." (PMID 30983992, 2019). "Irinotecan is a topoisomerase I (TOP1) inhibitor widely used in the treatment of colorectal cancers but only investigated for the use in metastatic BC in a very limited number of studies." (PMID 31196001, 2019). "Recently, cytotoxicity of hexadecanoic acid extracted from Kigelia pinnata leaves against human colorectal carcinoma has been demonstrated by interaction with DNA topoisomerase I." (PMID 30123207, 2018). "A level ID post-hoc biomarker correlative analysis of the FOCUS trial showed an overall survival benefit in a subset of colorectal cancer patients with moderate/high TOP1 levels measured by immunohistochemistry." (PMID 27888622, 2017). "TDP1 and TOP1 levels are key determinants of irinotecan response in colorectal cancer cells and TDP1 depletion has been shown to sensitise the RKO cell line to irinotecan by increasing the number of cytotoxic DSBs." (PMID 28180300, 2017). "Colorectal cancer cell lines exhibit sensitivity to irinotecan when harboring increased TOP1 gene copy number or increased TOP1/CEP20 ratio." (PMID 26875156, 2016).
colorectal cancer (continued). "The TOP1 gene, located at 20q12-q13.1, is frequently detected at elevated copy numbers in colorectal cancer (CRC)." (PMID 23577133, 2013). "TOP1 gene was reported as amplified in colorectal cancer using fluorescent in situ hybridization (FISH) technique." (PMID 23405089, 2013). "In the present review, we first describe and discuss experiences with topoisomerase I (Top1) measurements in colorectal cancer (CRC)." (PMID 24400218, 2013). "Colorectal cancer is the most thoroughly examined cancer with regard to Top1 expression and several studies have found increased Top1 protein in CRC tissues compared to non-cancerous tissues." (PMID 24400218, 2013). "In this work, we identify pevonedistat (PEV), a first-in-class inhibitor of neddylation recently approved for the treatment of high-risk myelodysplastic syndromes (HR-MDS), as synergistically cytotoxic with TOP1 inhibitors by high-throughput screens in human colorectal carcinoma cells." (PMID 37353483, 2023). "Another study revealed that copy number gains of TOP1 was found in colorectal cancers, which could affect the drug sensitivity of irinotecan and anthracycline." (PMID 36288358, 2022). "However, a role for TOP1 as an oncogene has been already strongly suggested, being found upregulated in different types of tumors, including breast, liver and colorectal cancers 83–86." (PMID 35197484, 2022). "Therefore, PTE has a greater potential to be further developed as an anti-tumor drug for the treatment of colorectal cancer through Top1/Tdp1-mediated DNA repair pathway." (PMID 34439157, 2021). "Overall, PTE and RE can inhibit the activity of Top1 enzyme and inhibit the DNA damage repair pathway mediated by Top1/Tdp1, and can effectively inhibit colorectal cancer development with low toxicity, thus they have great potential to be developed into a new generation of anti-tumor drugs." (PMID 34439157, 2021). "PTE and RE could inhibit the proliferation of various colorectal cancer cells and decrease Top1 and Tdp1 contents and mRNA expression in wild-type, constructed Tdp1 overexpressing CL187, Top1- or Tdp1- silenced CL187 cell lines." (PMID 34439157, 2021). "Furthermore, TOP1 depletion by siRNA was found to sensitize colorectal cancer cell lines to irinotecan treatment in a TOP1-dependent manner." (PMID 31547492, 2019). "For example, TOP1 was found to be associated with favorable prognosis in stage III colorectal cancer patients, while it did not have prognostic significance in gastric cancer patients." (PMID 28355294, 2017). "Recent research suggests that TOP1 gene copy number may be used as an alternative to TOP1 protein expression as a predictive biomarker for stratification of patients with CPT-responsive colorectal cancer." (PMID 31783818, 2019). "Amygdalin has been proven to lessen the expression of cell cycle-related genes in SNU-C4 colorectal cancer cells, such as exonuclease 1 (EXO1), topoisomerase (DNA) I (TOP1), subfamily F, and ATP binding cassette." (PMID 36618007, 2023). "Camptothecin (CPT) and its derivatives are clinically used as DNA topoisomerase I (TOP1) inhibitors for the treatment of ovarian, lung, and colorectal cancers." (PMID 36300094, 2022). "For colorectal cancer module, the analysis revealed the occurrence of approved drug targets TYMS, TOP1, BRAF and EGFR." (PMID 35053185, 2021). "Biological parameters influencing the response of human colorectal cancers (CRCs) to CPT-11, a topoisomerase 1 (top1) inhibitor, were investigated using a panel of nine CRCs xenografted into nude mice." (PMID 10732766, 2000). "Gain of chromosome 20 or 20q has been widely reported as a recurrent chromosomal abnormality in colorectal cancer, supporting the high frequency of TOP1 non-amplified gains observed in this study." (PMID 23577133, 2013).
colorectal cancer (continued). "Here, we generated colorectal cancer (CRC) cell models for irinotecan resistance and report that resistance is neither due to downregulation of the main cellular target of irinotecan TOP1 nor upregulation of the key TOP1 PDB repair factor TDP1." (PMID 28180300, 2017). "Though target quinolines demonstrated potent antiproliferative effect, specifically against colorectal cancer DLD-1 and HCT-116, they showed weak TOP1 inhibition which may be attributable to their non-coplanarity." (PMID 34923887, 2022).
colon cancer (34 papers, 2011 to 2025). "Specifically, TOP1 up-regulation in colon tumors is associated with decreased DoG RNA expression and conversely treating colon cancer cells with the anticancer TOP1 inhibitor CPT or TOP1 short hairpin RNA (shRNA) results in the induction of specific DoG RNAs." (PMID 38959318, 2024). "In the four HCT116-derived camptothecin-resistant colon cancer sublines, each with mutations in Top1 was demonstrated to decrease potency of camptothecin analogues, FL118 showed greater potency than SN-38 overall." (PMID 25928015, 2015). "Having found that colon cancer–associated TOP1 up-regulation is correlated with lower DoG RNAs levels, we hypothesized that the therapeutic benefits of inhibiting TOP1 activity with CPT may be linked to increased DoG RNA levels in colon cancer." (PMID 38959318, 2024). "Astragalus is a dimethylated derivative of resveratrol, which inhibits Top1 enzyme activity and treats colon cancer through the Top1/Tdp1-mediated DNA repair pathway with low toxicity." (PMID 40490812, 2025). "Third, we identify that DoG RNA induction is a consequence of treating colon cancer cells with the topoisomerase I (TOP1) poison camptothecin and following TOP1 depletion." (PMID 38959318, 2024). "Consistent with CPT being an effective therapeutic in treating advanced colon cancer in the clinic is the finding that TOP1 is significantly up-regulated in COAD tumors and high TOP1 expression is associated with high CPT sensitivity." (PMID 38959318, 2024). "We also reveal that TOP1-dependent dysregulation of DoG production has important implications in colon cancer." (PMID 38959318, 2024). "This is evidenced by the enhanced levels of DoG production in colon cancer cells that are observed following inhibition of TOP1 catalytic activity with CPT." (PMID 38959318, 2024). "Altogether, our results show that DPDT preferentially targets HCT116 colon cancer cells likely through DNA topoisomerase I poisoning." (PMID 37343056, 2023). "Taken together, our results show that DPDT preferentially targets HCT116 colon cancer cells likely through DNA topoisomerase I poisoning." (PMID 37343056, 2023). "We showed previously that CPT has a biphasic effect on nuclear R-loop levels, which is TOP1 dependent in HCT-116 colon cancer cells." (PMID 35794238, 2022). "In recent publications, we correlated each of ABCG2 and TOP1 mRNA expression to patient outcome in a subset of Stage III colon cancer patients enrolled in the PETACC-3 study." (PMID 32326511, 2020). "This study shows that the combination of ABCG2 and TOP1 gene expression significantly divided the Stage III colon cancer patients into two groups regarding benefit from adjuvant treatment with FOLFIRI but not 5FUL." (PMID 32326511, 2020). "Colon cancer cells treated with high doses of DNA topoisomerase I inhibitor, SN-38, and ovarian cancer cells exposed to poly(ADP-ribose) polymerase inhibitor, olaparib, behaved similarly." (PMID 32012719, 2020). "To test a potential contribution of TOP1 or TOP2 on TNFα-induced expression of inflammatory genes, we measured the impact of specific TOP1 inhibitors on TNFα-triggered gene expression in human diploid colon cancer HCT116 cells." (PMID 31242600, 2019). "CPT and its clinically used derivatives topotecan (TPT) or SN-38 are used for treatment of colon cancer, gynecologic malignancies and small-cell lung cancers, but also serve as tools to study the role of TOP1 in gene expression." (PMID 31242600, 2019). "In vitro studies with colon cancer cell lines have demonstrated a significant correlation between the topoisomerase I gene (TOP1) copy numbers (CN) or Top1 protein expression and the sensitivity to SN-38." (PMID 28077117, 2017). "In the present study we undertook a thorough investigation of the Top1 status in three human colon cancer cell lines with acquired resistance to SN-38 developed through approximately 9 months of drug exposure." (PMID 27029323, 2016).
colon cancer (continued). "Irinotecan is one specific topoisomerase I (TOP1) inhibitor, but down-regulation of TOP1 has been found in some colon cancer cases, leading to reduced therapeutic effect of irinotecan." (PMID 26460955, 2015). "(i) In total, 105 plants (33 edible) were found to interact with 4 target proteins (TEK, KDR, FGR1 and TOP1) of the FDA approved colon cancer drugs and 43 of their first-degree neighbors." (PMID 24886433, 2014). "Having identified that DoG RNAs are differentially expressed and exhibit clinical significance in colon cancer, we next examined whether the Food and Drug Administration–approved TOP1 inhibitor, CPT, alters DoG RNA expression." (PMID 38959318, 2024). "However, n-hexadecanoic acid affects colon cancer cell growth, while its ethyl ester derivative can inhibit the DNA topoisomerase I and is an apoptosis inductor in leukaemia and neuroblastoma cells." (PMID 30832627, 2019). "They found that amygdalin down‐regulated the cell cycle‐related genes: ATP‐binding cassette, exonuclease 1 (EXO1), sub‐family F and topoisomerase (DNA) I (TOP1) in SNU‐C4human colon cancer cells, thereby affecting tumor cell cycle, inhibiting cell proliferation and exerting its antitumor effect." (PMID 31066207, 2019). "We generated three SN-38-resistant human colon cancer cell lines and investigated Top1." (PMID 27029323, 2016). "Since molecular alterations in Top1 may result in resistance to irinotecan, we characterized Top1 in three human colon cancer cell lines with acquired resistance to SN-38." (PMID 27029323, 2016). "Another study using colon cancer cell lines found little correlation between total Top1 levels (as assessed by Western blotting) and efficacy, and concluded that the extent of Top1 cleavage complex (Top1cc) formation may be more informative." (PMID 23284638, 2012). "Thus, specific inhibitors of CUL4B could increase the level of TOP1 and consequently improve therapeutic effect of irinotecan on colon cancer." (PMID 26460955, 2015). "To examine a direct role for TOP1 in the inhibition of DoG RNA production, we next performed RNA-seq in SW480 colon cancer cells expressing shRNAs against TOP1." (PMID 38959318, 2024). "We engrafted three colon cancer cell lines (LS-1034, SW837 and SNU-81) in NOD/SCID mice and treated them for 24–35 days with irinotecan (TOP1 inhibitor), rabusertib (CHEK1 inhibitor), or with a combination of the two drugs." (PMID 35197630, 2022). "Similarly, reserpine, a natural compound that has found applications as antihypertensive and antipsychotic, exhibits activity against DNA topoisomerase I - the target of the colon cancer drug irinotecan - which could be interesting to investigate further in the light of drug repurposing." (PMID 24453957, 2014). "Together, these findings underscore the importance of relieving the TOP1-dependent block of DoG production in colon cancer, which is overcome by CPT and TOP1 knockdown and therefore may have therapeutic implications in colon cancer." (PMID 38959318, 2024). "Consistent with a direct role for TOP1 in regulating DoG production is our finding that TOP1 depletion, similar to TOP1 inhibition with CPT, results in genes that escape transcriptional termination and support high levels of DoG production in colon cancer cells." (PMID 38959318, 2024). "Using SW480 colon cancer cells, we performed chromatin immunoprecipitation followed by deep sequencing (ChIP-seq) for RNAPII and TOP1 and measured TOP1 catalytic activity using TOP1 sequencing (TOP1-seq), a method for identifying only catalytically engaged TOP1 (TOP1cc)." (PMID 38959318, 2024). "Detailed insights into TOP1-DPCR at the organism level are important for biomedicine, because TOP1-DPC inducers, the CPT derivatives irinotecan and topotecan, are used to treat various cancers including ovarian and colon cancers, small-cell lung cancer, central nervous system tumours and sarcomas." (PMID 37788708, 2023).